POLA1 (DNA polymerase alpha 1, catalytic subunit)
Diseases named in the same sentence as POLA1 in open-access papers:
POLA1 is named in the same sentence as 56 diseases in open-access papers, as found by Europe PMC text mining. Sharing a sentence is not in itself a finding about the gene and the disease. The quoted sentences say what the papers report.
colorectal cancer (6 papers, 2013 to 2024). A primary or metastatic malignant neoplasm that affects the colon or rectum. "First, we applied a model of ATR-deficient DLD-1 human colorectal cancer cells to confirm synthetic lethality by using chemical POLA1 inhibition." (PMID 39128273, 2024). "To verify the synthetic lethal interaction between ATR and POLA1 we initially applied a well-described model of ATR-deficient DLD-1 human colorectal cancer cells." (PMID 39128273, 2024). "To model POLA1 deficiency, we applied ST1926, an atypical retinoid that has already been shown to inhibit POLA1 and proliferation of colorectal cancer cells." (PMID 39128273, 2024). "ST1926, an atypical retinoid, showed a potent antitumor activity in colorectal cancer and also inhibited DNA polymerase α activity with decreased POLA1 protein expression levels." (PMID 37175782, 2023). "In addition, studies showed that colorectal cancer cells which are resistant towards ST1926 and its parent molecule CD437 develop POLA1 mutations." (PMID 39128273, 2024). "Of note, our data demonstrating increased sensitivity of ATR/CHK1 inhibitors in POLA1 depleted cells are strongly supported by already published data showing synthetic lethality between CHK1 and B-family DNA polymerase including POLA1 in both lung and colorectal cancer cells." (PMID 39128273, 2024). "Furthermore, mutations in POLA1 were found in the cells that became resistant to ST1926, suggesting POLA1 as a potential target in colorectal cancer treatment." (PMID 37175782, 2023). "Second, mutations in the gene encoding DNA polymerase α (known as POLA1) led to the resistance of colorectal cancer to CD437 and its analogues, regardless of the RAR signaling status." (PMID 36012706, 2022). "Thus, siRNA-mediated POLA1 depletion induced similar effects as did ST1926 in ATR-deficient cells, further supporting our hypothesis of synthetic lethality between ATR and POLA1 in colorectal cancer cells." (PMID 39128273, 2024). "Taken together, these data illustrate a synthetically lethal relationship between ATR and POLA1 through simultaneous impairment of ATR and POLA1 in DLD-1 colorectal cancer cells." (PMID 39128273, 2024). "Consistent with the idea that replication stress dictates CHKi response, silencing of multiple DNA polymerase isoforms, including POLA1, POLE, and POLE2, enhances replication stress and increases CHK1i sensitivity in lung and colorectal cancer cell lines." (PMID 35444937, 2022). "In silico analysis of normal and malignant tissue expression data revealed that POLA1 levels are increased in colorectal cancer cells and tissues compared to non-transformed cells." (PMID 37175782, 2023). "Similarly, DNA replication gene knockout may improve CHK1i activity, by inhibiting POLA1, POLE, and POLE2 genes in a siRNA screen performed on lung and colorectal cancer cells showing low sensitivity to CHK1i60." (PMID 38555285, 2024).
X-linked reticulate pigmentary disorder (6 papers, 2020 to 2024). "Notably a specific intronic variant in POLA1 causing an X-linked reticulate pigmentary disorder, is also associated with recurrent pneumonias and chronic diarrhea, with underlying immunodeficiency alongside autoinflammation." (PMID 33060134, 2020). "Support for this possibility comes from research on X-linked reticulate pigmentary disorder (XLPDR), an orphan genetic disease caused by mis-splicing mutations in the POLA1 gene resulting in partial POLA1 protein deficiency." (PMID 39231808, 2024). "Of note, mutations in POLA1 have been found in patients presenting a multisystemic disorder without neurological symptoms, named X-linked reticulate pigmentary disorder (PDR; MIM 301220)." (PMID 35328505, 2022).
hypogonadism (3 papers, 2019 to 2024). A disorder characterized by decreased function of the gonads. "More recently, other mutations in POLA1 have been reported, which result in severe intrauterine and postnatal growth retardation, intellectual disability, hypogonadism, and in at least 1 case, recurrent serious infections and chronic IFN activation." (PMID 31672938, 2019). "Interestingly, POLA1 was recently associated with X-Linked ID associated with severe growth retardation, microcephaly, and hypogonadism." (PMID 34976023, 2021). "Finally, it is worth noting that severe POLA1 deficiency leads to hypogonadism, whereas MCM4 mutations lead to adrenal insufficiency, both states of reduced steroid hormone production." (PMID 31672938, 2019).
cervical cancer (2 papers, 2021 to 2023). A primary or metastatic malignant neoplasm involving the cervix. "Our research provides a co-expression network of gene modules and identifies TIPIN and POLA1 as stable potential prognostic biomarkers for cervical cancer." (PMID 33816217, 2021). "This module's four proteins, MCM2, MCM10, POLA1, and TONSL, are cervical cancer driver genes based on the DriverDBv3 report." (PMID 37746664, 2023). "The logFC values of the MCM2, MCM10, POLA1, and TONSL in cervical cancer versus normal groups are 2.3, 3.37, 1.76, and 0.587, respectively." (PMID 37746664, 2023). "Tissue samples from cervical cancer were picked out in the Human Protein Atlas and the expression levels of TIPIN and POLA1 were confirmed by immunohistochemistry." (PMID 33816217, 2021). "Hierarchical clustering and Gepia results indicated that the expression quantity of hub genes NDC80, TIPIN, MCM3, MCM6, POLA1, and PRC1 may determine the prognosis of cervical cancer." (PMID 33816217, 2021).
colon cancer (2 papers, 2023 to 2024). "Although such a correlation is not yet known for POLA1, POLA1 mutations are found in 6,7 % of tested colon cancer samples and in 22 out of 55 tested colon cancer cell lines according to Catalogue of Somatic Mutations In Cancer and Cell (COSMIC) by Sanger Institute." (PMID 39128273, 2024).
gastric cancer (2 papers, 2018 to 2024). A primary or metastatic malignant neoplasm involving the stomach. "For instance, BioPathNet’s path gradients clarify drug-disease associations, such as Bosutinib for ALL and Acitretin for gastric cancer, and highlight key paths and genes like SMC1A and POLA1 in Clofarabine’s mechanism." (PMID 39372928, 2024).
glioma (2 papers, 2023). A benign or malignant brain and spinal cord tumor that arises from glial cells (astrocytes, oligodendrocytes, ependymal cells). "Current studies on the role of POLA1 or TIAM1 in glioma cells or mesenchymal stem cells are limited; thus, further studies should focus on these issues." (PMID 37005685, 2023). "Overall, the expression of LIN9, MCM8, CEP72, POLA1, DBF4, NDE1 and CDKN2C increase the prognostic risk for patients with glioma." (PMID 37349788, 2023). "Our analysis revealed a significant positive correlation between E2F4 and MCM8, POLA1, DBF4, NDE1 or CDKN2C expression in primary gliomas." (PMID 37349788, 2023). "The correlation between E2F4 and LIN9, MCM8, CEP72, POLA1, DBF4, NDE1 or CDKN2C expression in glioma tissues was analyzed using CGGA." (PMID 37349788, 2023).
immune deficiency (2 papers, 2020 to 2024). "Finally, mutations in genes encoding subunits of the replicative DNA polymerases POLA1, POLD1, POLD2, POLE, and POLE2 have implicated components of the active replisome in primordial dwarfism, often with immune deficiency, and in the case of POLE, adrenal failure." (PMID 33060134, 2020).
lung carcinoma (2 papers, 2016 to 2024). "For example, an RS signature including genes involved in DNA polymerases (POLA1, POLD4, POLE4) was found to be predictive for ATRi response in lung cancer preclinical models." (PMID 38555285, 2024).
microcephaly (2 papers, 2020 to 2021). A congenital or acquired developmental disorder in which the circumference of the head is smaller than normal for the person's age and sex. "Most individuals with MPD caused by POLA1 variants have growth retardation and microcephaly without such features, and facially PRIM1 deficiency appears distinct from these and individuals with POLE-associated IMAGe syndrome." (PMID 33060134, 2020).
ovarian carcinoma (2 papers, 2024 to 2025). A malignant neoplasm originating from the surface ovarian epithelium. "SNRPB promotes ovarian cancer growth and metastasis by inhibiting POLA1 and BRCA2 exon 3 skipping." (PMID 39910288, 2025).
age-related macular degeneration (1 paper, 2021). Age-related loss of vision in the central portion of the retina (macula), secondary to retinal degeneration. "WEE1, SMC2, HMGB1, RRM2, and POLA1 proteins were also observed to be involved in the progression and invasion of retinoblastoma; SLC24A2 and DTX4 in age-related macular degeneration; and EPHB6, EFNB3, and SHC1 in glaucoma." (PMID 34646884, 2021).
Autoimmunity (1 paper, 2019). The occurrence of an immune reaction against the organism's own cells or tissues. "Of added interest, an autoimmunity pathway is present in Panel I with proteins LRP1 and POLA1." (PMID 31026304, 2019).
bladder cancer (1 paper, 2017). "Moreover, CSTF2, POLA1, HMOX2, and EFNB2 may be associated with the prognosis of bladder cancer patient." (PMID 28320388, 2017). "HMOX2 (heme oxygenase-2), CSTF2 (cleavage stimulation factor, 3′ pre-RNA, subunit 2, 64 kDa), and POLA1 (polymerase (DNA directed), alpha 1) were the three obviously significant related genes, and a marginal significant correlation was found between EFNB2 (ephrin-B2) and prognosis of bladder cancer." (PMID 28320388, 2017).
glioblastoma (1 paper, 2023). The most malignant astrocytic tumor (WHO grade IV). "These identified novel proteins may be potential therapeutic targets for new drug development in glioblastomas, especially using POLA1 inhibitors." (PMID 37762371, 2023).
liver cancer (1 paper, 2021). An epithelial or non-epithelial malignant neoplasm that arises from the liver. "But other studies have shown the carcinogenic activity of PolA1 in bladder and liver cancer." (PMID 34646884, 2021).
lymphoma (1 paper, 2013). A malignant (clonal) proliferation of B- lymphocytes or T- lymphocytes which involves the lymph nodes, bone marrow and/or extranodal sites. "The difference in the expression patterns of genes between the healthy and DLBCL samples in the canine dataset highlighted important lymphoma-specific up-regulated genes including DHFR, MS4A1, MYC, POLA1, POLE, RRM1, TOP2A and TYMS." (PMID 24023754, 2013).
metastatic carcinoma (1 paper, 2021). A carcinoma which has spread from the original site of growth to another anatomic site. "The results showed that gene expression in metastatic carcinoma was lower than that in cancer primary cells, which indicated that lower gene expression of TIPIN and POLA1 was correlated with poor clinical outcomes." (PMID 33816217, 2021).
pancreatic cancer (1 paper, 2024). "Vice versa, as POLA1 mutations occur in about 7 % of colorectal and pancreatic cancer samples, we additionally used four different ATR and CHK1 inhibitors to assess the chemical inducibility of synthetic lethality in various POLA1-depleted colon and pancreatic cancer cell lines." (PMID 39128273, 2024).
retinoblastoma (1 paper, 2021). A malignant tumor that originates in the nuclear layer of the retina. "The STRING database plotted their protein network, and the five proteins WEE1, SMC2, HMGB1, RRM2, and POLA1 that were most associated with the range of activity involved in tumorigenesis and retinoblastoma progression were selected from 366 genes." (PMID 34646884, 2021). "As shown in the protein network plot for retinoblastoma-related genes, SMC2, HMGB1, WEE1, RRM2, and POLA1 proteins showed an association with other proteins." (PMID 34646884, 2021).
telomere syndrome (1 paper, 2021). Accelerated aging syndromes often caused by inheritable gene mutations resulting in decreased telomere lengths. "K242A and K240A hinder PolA1 association with CTC1 in a manner similar to telomere syndrome-associated mutations A227V and V259M14." (PMID 33731801, 2021). "Two mutations associated with the telomere syndromes Coats Plus and DC, A227V and V259M, were previously shown to halt nuclear localization and diminish PolA1 and PolA2 association with CST14." (PMID 33731801, 2021).
X-linked dyskeratosis congenita (1 paper, 2024). "It indicates a critical role for POLA1 in bone marrow cell proliferation/survival and is reminiscent of previous observations in X-linked dyskeratosis congenita due to variants in DKC1." (PMID 39198715, 2024).
cancer (16 papers, 2012 to 2025). A tumor composed of atypical neoplastic, often pleomorphic cells that invade other tissues. "Our results illustrate a novel potential approach for individualized cancer therapy using specific ATR/CHK1 inhibitors or POLA1 inhibitors for the individualized treatment of ATR- or POLA1-deficient tumors, respectively." (PMID 39128273, 2024). "Analyzing cell cycle and apoptotic markers via FACS and Western blotting, we were able to show that apoptosis and S phase arrest contributed to the increased sensitivity of ATR-deficient cancer cells towards POLA1 inhibitors." (PMID 39128273, 2024). "If POLA1 is thus inhibited in ATR- or CHK1-deficient cancer cells, global RPA exhaustion and therefore replication catastrophe culminating into apoptosis might be the consequence." (PMID 39128273, 2024). "Therefore, it would be interesting to analyze the effects of POLA1 inhibitors specifically in cancer cells harboring these mutations." (PMID 39128273, 2024). "Conversely, we demonstrated that siRNA-mediated POLA1 depletion sensitized several cancer cell lines towards chemical inhibition of ATR and its main effector kinase CHK1." (PMID 39128273, 2024). "ST1926 was shown to mediate its antitumor activities through DNA damage induction, mainly by inhibiting POLA1 activity in cancer cells." (PMID 37762371, 2023). "The observed changes in POLA1 in multiple cancers suggest that a more detailed understanding of the roles that POLA1 plays in these cancers should aid in the development of effective therapies." (PMID 37175782, 2023). "According to a series of analysis, TIPIN and POLA1 were recognized to both participate in cancer progression of CC." (PMID 33816217, 2021). "POLA1 has antitumor activity in inhibiting cancer cell proliferation and inducing apoptosis." (PMID 40165902, 2025). "To test whether our data initially obtained in DLD-1 were generalizable beyond one cell line or tumor entity, we next assessed whether POLA1 depletion also sensitized other cancer cell lines towards ATR/CHK1-inhibition." (PMID 39128273, 2024). "In conclusion, our study suggests that the synthetically lethal effects of simultaneous impairment of ATR and POLA1 in cancer cells might represent a novel and promising approach for individualized cancer therapy." (PMID 39128273, 2024). "In conclusion, the synthetic lethality between ATR/CHK1 and POLA1 might represent a novel and promising approach for individualized cancer therapy: First, alterations of POLA1 could serve as a screening parameter for increased sensitivity towards ATR and CHK1 inhibitors." (PMID 39128273, 2024). "In addition, CD19 and POLA1 have been reported as targets for anti-cancer therapy." (PMID 35563525, 2022). "Finally, our data reveals insights into how mutations within CST or PolA1 may result in a loss of CST function for certain telomeropathies and cancers." (PMID 33731801, 2021).
tumor (11 papers, 2016 to 2025). "Among DNA repair genes, we detected evidence of positive selection in the tumor suppressor-encoding PALB2 and in four DNA polymerase-encoding genes (POLA1, POLD1, POLK, and POLM)." (PMID 37728212, 2023). "Next, we examined the effect of ST1926 on POLA1 protein levels since ST1926 was shown to exert its anti-tumor effect through POLA1 inhibition." (PMID 37762371, 2023). "The expression levels of MCM7, CDK6 and POLA1 showed a remarkably elevated trend according to the grade of the tumor, and differences between all grades were statistically significant." (PMID 37005685, 2023). "This is likely explainable by the highly heterogenous mutation patterns of different tumor cell lines, some of which could harbor mutations that overrule the synthetically lethal effects between ATR/CHK1 and POLA1." (PMID 39128273, 2024). "POLA1 is a subunit of DNA polymerase α, involved in DNA synthesis, and its abnormal expression may affect the genetic stability and immunogenicity of tumor cells." (PMID 39083127, 2024). "We have shown that ST1926 targets POLA1 and suppresses tumor growth in CRC models." (PMID 37762371, 2023). "Therefore, altered POLA1 expression could potentially also serve as indicator for tumor response after treatment with CHK1 inhibitors." (PMID 39128273, 2024). "The increased DNA 5mC level and expression of genes including POLA1 promoted PDAC cell proliferation, colony formation, spheroid growth, and tumor development in mice." (PMID 37488138, 2023). "Moreover, we collected tumor tissues and adjacent normal colorectal tissues from CT26 tumor-bearing mice in vivo for Pola1 qPCR experiments." (PMID 40083927, 2025). "Key genes such as MCM4, POLA1 and MCM6 are closely related to tumor immune invasion." (PMID 39083127, 2024).
neurodevelopmental disorder (1 paper, 2023). A behavioral and cognitive disorder with onset during the developmental period that involves impaired or aberrant development of intellectual, motor, or social functions. "POLA1 has been related to blood traits and neurodevelopmental disorders, but its association with impulsivity is novel." (PMID 37173343, 2023).
POLA1 also shares sentences with these, for which no sentence is quoted: infection (11 papers); syphilis (8); latent syphilis (3); neurosyphilis (2); rectal cancer (2); ulcer (2); Adrenal insufficiency (1); AIDS (1); astrocytoma (1); bone marrow failure (1); brain glioma (1); breast carcinoma (1); COVID-19 (1); developmental delay (1); Epstein-Barr virus infection (1); genetic disease (1); Genital ulcers (1); glaucoma (1); hepatocellular carcinoma (1); HIV-1 infection (1); Hypertension (1); IMAGe syndrome (1); immunodeficiency (1); Intellectual disability (1); malignant pleural mesothelioma (1); melanoma (1); pneumonia (1); Skin rash (1); Skin ulcer (1); tuberculosis (1).
A further 1 disease shares a sentence with POLA1 in 1 paper.